VDAC1P8 (voltage dependent anion channel 1 pseudogene 8)
Gene: Transcribed processed pseudogene on chromosome 6 (143,490,515 to 143,491,367, forward strand). Ensembl gene ENSG00000229036.
Diseases named in the same sentence as VDAC1P8 in open-access papers:
VDAC1P8 is named in the same sentence as 5 diseases in open-access papers, as found by Europe PMC text mining. Sharing a sentence is not in itself a finding about the gene and the disease. The quoted sentences say what the papers report.
chronic lymphocytic leukemia (1 paper, 2023). "Taken together, these results highlight that VDAC1P8 is closely associated with leukemia, a finding mentioned in the literature when cancer-specific pseudogenes were identified in chronic lymphocytic leukemia." (PMID 37344914, 2023).
leukemia (1 paper, 2023). A malignant (clonal) hematologic disorder, involving hematopoietic stem cells and characterized by the presence of primitive or atypical myeloid or lymphoid cells in the bone marrow and the blood. "Since in leukemia the expression of VDAC1P8 is considerably higher than in healthy tissue, this pseudogene could be responsible for, or at least contribute to, the down-regulation of VDAC1 in AML." (PMID 37344914, 2023).
tumour (1 paper, 2023). "Also, VDAC1P8 is downregulated in almost all tumour tissues considered, compared with its normal counterpart." (PMID 37344914, 2023). "Interestingly, only the pseudogenes VDAC1P8 and VDAC1P11, upregulated in AML, have binding sites for transcription factors involved in development of the tumor counterpart." (PMID 37344914, 2023).
VDAC1P8 also shares sentences with these, for which no sentence is quoted: acute myeloid leukemia (1 paper); cancer (1).